CD4 (CD4 molecule)
Diseases named in the same sentence as CD4 in open-access papers (continued):
Sharing a sentence is not in itself a finding about the gene and the disease.
tumor (continued). "In OSCC, T lymphocytes are the principal components of tumor-infiltrating lymphocytes (TILs), and high numbers of CD8 and CD4 T cells have both been reported to correlate with longer patient survival." (PMID 36077836, 2022). "The system displayed that the repolarization of macrophages in TDLNs occurred as well as the proliferation and activity of CD4+ and CD8+ T cells in tumor sites, thus remarkably preventing tumor proliferation and metastasis." (PMID 35745800, 2022). "Further combination of the vaccine with a chemokine inhibitor, reparixin, significantly increased the infiltration of CD4+ and CD8+ T cells into the tumor environment, while the antitumor effect was significantly enhanced." (PMID 35805071, 2022). "CD4+ CD25+ regulatory T cells are a subgroup of CD4+ T cells, which play a special role in tumor immune escape." (PMID 35047040, 2022). "Here, we found that the high expression of PD-L2 in the stroma significantly increased the number of tumor-related CD68+ macrophages and CD4+Foxp3+ Treg regulatory T lymphocytes." (PMID 36606190, 2022). "The results indicated that CDCA8 expression was significantly positively correlated with tumor purity, infiltration levels of B cells, CD8+T cells, CD4+T cells, and macrophages in PCa." (PMID 35449575, 2022). "Tumor infiltration analyses revealed a direct correlation between upregulated genes and CD8+, CD4+ T cells, and B cells and inversely correlated with myeloid-derived suppressor cells." (PMID 36428698, 2022). "Immune suppression within the tumor microenvironment (TME) has been demonstrated as an integral barrier to the efficacy of immunotherapy, impairing the ability of tumor-specific CD4+ or CD8+ T cells to respond with maximal activation or effector function." (PMID 36453551, 2022). "Predominance of CD4+ and CD8+ T cell infiltration into the tumor bed is a positive predictive marker for the outcome of targeted therapies and is associated with a favorable prognosis in patients with BC." (PMID 35710296, 2022). "Additionally, we found that attenuated tumor growth in LEC MHC-II knockout background was associated with an overall improved tumor-specific immune response as characterized by increased numbers of tumor-specific CD8+ and effector CD4+ T cells, as well as decreased numbers of Tregs locally." (PMID 36362253, 2022). "We also assessed polyclonal IL-2/IFN-γ-producing CD4+ and CD8+ T cells that support anti-tumor immunity." (PMID 36876140, 2022). "After the PDT effect was achieved under light, the anti-PD-L1 antibody was further administrated to realize the combined treatment of PDT and ICB, thus leading to increased CD4+ and CD8+ T cells that can specifically eliminate tumor cells." (PMID 35910806, 2022). "Further T cell profiling of PBMCs by flow cytometry demonstrated strong proliferation (Ki67+) of CD4+ and CD8+ T cells in patients with tumor control." (PMID 36106631, 2022). "Moreover, in in vivo preclinical tumor models, anti-PD-1 therapy can exacerbate high TGFβ signaling through activation of another checkpoint on exuberant T cell activation, the secretion of TGFβ1 from activated CD4+ T helper type 1 (Th1) cells, as well as other mechanisms." (PMID 36382146, 2022). "Animal experiments have shown that: DHZCW can induce tumor cell apoptosis by reversing the balance of Treg/TH1, which are derived from naive CD4+T cells, but one of them has a negative regulation on immunity, while the other has a positive effect on immunity." (PMID 36118529, 2022). "Since ICOS is expressed on CD4+ T cells, CD8+ T cells, and NK cells, we aimed to investigate which cell populations are critical for tumor control by radiation therapy and ICOS antibody." (PMID 36056093, 2022). "In a mouse tumor model, NK cells activated at a distant site by a TLR7/8 agonist released tumor antigens and induced tumor-specific CD4+ T cells." (PMID 35768424, 2022).
tumor (continued). "The percentage of CD4+ T cells and CD8+ T cells was increased while that of Foxp3+ cells was decreased in the tumor tissues of CRC mice colonized with microbiota from healthy individuals." (PMID 36726985, 2022). "NSCLC tumors in females have increased infiltration of CD4+ T cell populations, suggesting that MHC-II driven pathways are central to the anti-tumor immune response in females." (PMID 35992816, 2022). "In the MRG-high subgroup, neutrophils and anti-tumor immune cells, such as CD8+ T cells, activated memory CD4+ T cells, and M1 macrophages, were more abundant." (PMID 36293001, 2022). "Siglec-9, a cell surface transmembrane receptor mainly expressed on B cells, CD56+ NK cells, and CD4+ and CD8+ T cells, is strongly related to the tumor immune microenvironment." (PMID 35372497, 2022). "Inhibition of adenosine generation decreased tumor growth in spontaneous and established models and is correlated with increased activated CD8+, CD4+ T cells and macrophages, implicating anti-CD73 immunotherapy in PDAC patients with high CD73 expression." (PMID 35360246, 2022). "We noted a statistically significant correlation between EBV DNA copy number/μg DNA and PD-1 expression on the CD8+ T cells in the blood samples as well as on the CD4+ and CD8+ T cells in the tumor and lymph node samples." (PMID 35158748, 2022). "The immune cell markers in LUAD were further studied, after correction of tumor purity, BTN3A2 in LUAD was significantly positively correlated with gene markers in B cells, CD8+ T cells, CD4+ T cells, macrophages, neutrophils, and dendritic cells." (PMID 35873496, 2022). "We explored the infiltration of lymphocytes in both tumors and the results showed that the orthotopic tumors had less infiltration of CD4+ and CD8+ T-cells, which is consistent with the cold tumor characteristics." (PMID 35874730, 2022). "Of note, the percentage of CD8+, CD4+CD8+ and γδ+ cells also decrease in tumor samples (p < 0.0001)." (PMID 36551555, 2022). "Pan-cytokeratin staining was used to identify epithelial populations within tumor samples, while CD4 and CD8 staining was used to identify tumor-infiltrating T cells." (PMID 35831288, 2022). "Tregs play vital roles in tumor progression by restraining different types of effector lymphocytes such as CD8+ CTLs and CD4+ T cells." (PMID 35935577, 2022). "Using this process, colorectal tumor cells have been shown to acquire immune receptors (e.g., CD45 and CD4) and functional immunoregulatory molecules (e.g., Tim3, CTLA-4 and PD-1) from T cells, thus enhancing tumor immunosuppression." (PMID 35269922, 2022). "Ligand TNF and its receptor TNFRSF1B were found to act as major signaling from CD4+ T cells to CD8+ T2/T3 cells, and the ability of the TNF–TNFRSF1B pair to kill tumor cells in vitro has been reported before." (PMID 35812372, 2022). "To determine the expression of TPX2 in different subsets of T cells, we separately isolated CD3+, CD4+, and CD8+ T cells from tumor-infiltrating lymphocytes (TILs) and peripheral blood mononuclear cells (PBMCs) from ten HCC patients." (PMID 35273149, 2022). "Blocking of M3R significantly improved immune response against cancer, as noted by the increased expression of CD4+ and CD8+ T cells leading to reduced tumor size, weight, and volume." (PMID 36614038, 2022). "The immune infiltration cells, such as CD8+ T cell, B cell, CD4+ T cell, neutrophil, and macrophage, secrete various factors that influence the TME, regulate tumor behaviors, and have anticancer ability." (PMID 35069733, 2022). "Unexpectedly, in vivo depletion of CD4+ T cells alone resulted in complete regression of EO771 tumors, while the combination of Anlotinib and anti-PD-1 therapy only slowed down EO771 tumor growth." (PMID 35990640, 2022). "ECE also dampened the suppressive strength of gMDSC on CD4 and CD8 cell proliferation, which are crucial for anti-tumor immunity." (PMID 36230591, 2022).
tumor (continued). "Although immunohistochemical staining has shown the presence of CD3+CD4+ T cells and CD3+CD8+ T cells, this coincides with expression of T-cell and tumor-derived immunosuppressive features." (PMID 36249685, 2022). "The TIMER database further showed that the expression of BAIAP2L2 in LIHC was positively correlated with tumor infiltrating cells, including B cells, CD8+ T cells, CD4+ T cells, macrophages, and DCs." (PMID 36338652, 2022). "The antibody promotes apoptosis in intratumoral Treg cells, increases tumor infiltration of CD8+ T cells, and favors the production of antitumor cytokines in CD8+ and CD4+ TILs." (PMID 36568966, 2022). "Flow cytometry results showed that the proportion of CD4+ T cells and CD8+ T cells in tumor of mice in vaccine group was higher than that in control group, especially the CD4+ T cells." (PMID 35748951, 2022). "There was a negative correlation between the galanin expression and T cell CD8+, CD4+, neutrophil and natural killer (NK) cell numbers in the COAD tumor microenvironment (TME)." (PMID 35707368, 2022). "Previous study indicated that SEC1 promoted the differentiation of CD4+ and CD8+ T cells to inhibit tumor growth in mice models." (PMID 36131929, 2022). "All these in vitro results were correlated with in ovo findings based on the CAM assay: pembrolizumab inhibited H460 tumor growth and induced evident chicken immune cell infiltration (with significant chicken CD45, CD3, CD4, CD8 and CD56 markers) in tumors." (PMID 35804865, 2022). "With late-stage subcutaneous BR-Luc xenografts, AGF94 treatment resulted in substantial anti-tumor efficacy, accompanied by significantly decreased M2-like FRβ-expressing macrophages and increased CD3+ T cells, whereas CD4+ and CD8+ T cells were unaffected." (PMID 35790779, 2022). "Treg depletion by diphtheria toxin administration in a transgenic model reactivates proliferation of both CD4+ and CD8+ T cells within TLS and results in enhanced tumor destruction." (PMID 35874810, 2022). "The combination therapy increased CD8+:CD4+ ratios and led to an increase in serine protease granzyme B, Ki67, and killer cell lectin like receptor G1 (KLRG1) in tumor infiltrating CD8+ cells." (PMID 36203599, 2022). "They regulate anti-tumor immune responses by activating cytotoxic CD8+ and Th1 CD4+ T-cells and by producing a range of cytokines." (PMID 36555392, 2022). "CD4+ T cells can either suppress or promote the antitumor cytotoxic CD8+ T cell responses, either in secondary lymphoid organs or in the tumor." (PMID 35008422, 2022). "MYC oncogenes also promote tumor formation by inducing immune escape, and treatment with Myc-ASO increases the number of CD4+ T cells and reshapes the tumor microenvironment." (PMID 36569303, 2022). "GBM samples were immune stained for CD4 and CD8 to evaluate CD4 and CD8+ lymphocytes in both the center of the tumor and in the healthy surrounding areas." (PMID 36611806, 2022). "We evaluated the distribution of CD4+ T cells and CD8+ T cells in tumor tissues, which was considered to reflect adaptive immune response during cancer therapy." (PMID 35762456, 2022). "Of note, CD8+ T cell cytotoxicity largely depends on CD4+ TRM cells, which can also hinder tumor growth via IFN-γ production or by tumor cell elimination." (PMID 36305904, 2022). "The expression of VISTA was found in tumor cells, CD68 + TILs, and CD4+ TILs in tissues of esophageal adenocarcinoma." (PMID 35669786, 2022). "Tumor-infiltrating immune cells (TIICs) mainly include CD8+ T cells, CD4+ T cells, B cells, neutrophils, macrophages, and dendritic cells, which account for a large proportion of TME." (PMID 36105715, 2022).
tumor (continued). "B cells have the ability to directly present antigens to CD4+ and CD8+ T cells, shaping their ability to mount antigen-specific immune responses in the context of tumor microenvironment." (PMID 36620544, 2022). "As MHC-II molecules are crucial for CD4+ T cell activation, MHC-II expression in tumour cells is beginning to gain traction in the field of immunotherapy and cancer vaccines." (PMID 36259237, 2022). "CD4+, CD8+ and activated CD8+ T cell infiltration to the tumor microenvironment was also demonstrated by flow cytometry and IHC staining." (PMID 36499455, 2022). "CD3, encompassing both CD8 and CD4 T-helper cells and CD8 cells, also have different densities in different areas of the tumor, and the evaluation has to be done twice for each of these markers on consecutive slides." (PMID 35267475, 2022). "Tumor-specific CD8+ T cells, CD4+ T cells, and B cells have all been described in extracranial tumors, but the prevalence, phenotype, and antigen specificity of these cells in BrMs is unclear." (PMID 35584630, 2022). "It is expressed on activated CD4 and CD8 T cells but also on NK cells, B cells, neutrophils, dendritic cells, eosinophils, mast cells, endothelial cells, and some tumor cells." (PMID 36591244, 2022). "Previous studies have shown that hot tumors reflect good immunogenicity, and CD4+T and CD8+T cells continue to infiltrate into tumor stroma, para-tumoral areas and tumor nests." (PMID 35464860, 2022). "In vivo depletion of CD4+ and CD8+ T cells simultaneously or CD8+ T cells alone partially reversed tumor growth inhibition induced by the combination of effective low-dose Anlotinib and anti-PD-1 therapy in EO771 tumors." (PMID 35990640, 2022). "Upon capturing tumor antigens, DC present the fragments at their surface, thus, activating differentiation of the naïve CD4+ and CD8+ T cells into tumor-specific effector T cells." (PMID 36143308, 2022). "In the TLS region, CXCL13 was highly coexpressed with CD4+ T cells, whereas CD8+ T cells predominantly expressed CXCL13 in the tumor and stromal regions." (PMID 35552285, 2022). "All the samples demonstrated positive staining for CD4+ and CD8+ cell infiltrates diffused in tumour stroma." (PMID 36612217, 2022). "Proficient MMR (pMMR) tumours showed a significantly higher abundance of total CD4+, CD68+, CD20+ and CD66b+ cells than dMMR tumours." (PMID 35982052, 2022). "By secreting tumor-related factors and extracellular vesicles (EVs) into the tumor microenvironment, tumors may also trigger the dysfunction and exhaustion of a variety of immune cells, such as CD4+ T cells, CD8+ T cells, natural killer (NK) cells, and dendritic cells (DC)." (PMID 36499501, 2022). "In this review, the presence of several T cells-subtype (CD4+, CD8+, CD3+ majorly) was shown, both within the tumour as well as surrounding the tumour, by T-lymphocyte-based immunoscore (a novel prognostic tool focused on the presence of several T cells)." (PMID 35406451, 2022). "GV1001 induces a CD4/CD8 T-cell response against cancer cells, yielding an immunological anti-tumor effect." (PMID 35281880, 2022). "In our current study, low risk patients were characterized by higher infiltration levels of activated CD4 T cells, CD8 T cells and B cells with anti-tumor potency." (PMID 36685946, 2022). "Compared with controls, the infiltration of CD3+CD4+ T cells, CD3+CD8+ T cells, and NK cells was significantly increased by 2-fold, 2-fold, and 4-fold, respectively, in the tumor tissue." (PMID 36102418, 2022). "We also examined the baseline tumor size, blood CD8+ and CD4+ T cells proportions, and plasma IFN-γ levels in different response groups and did not observe a significant difference." (PMID 36059644, 2022). "Similar to our previous data, in the B16 tumor model, the proportion of CD8+ T and CD4+ T cells in the SnSe NS-treated group was increased." (PMID 36500643, 2022).
tumor (continued). "Most tumor-infiltrating lymphocytes in solid tumors are of the CD3+ T-cell phenotype, including CD4+ helper cells, CD4+ regulatory T-cells and CD8+cytotoxic T lymphocytes (CTLs)." (PMID 36362598, 2022). "While CD4 CTL are now recognized to be of vital importance in anti-viral and anti-tumor immune responses, they can also contribute to chronic inflammatory pathologies." (PMID 35903098, 2022). "The main subgroups of T lymphocytes are the so-called “Helper T-Cells” (CD4+), “Cytotoxic T-Cells” (CD8+), and “Regulatory T-Cells” (CD4+, CD25+ and FOXP3+), playing a role in controlling tumor growth." (PMID 36139508, 2022). "The tumor progression was related to an increase in the number of TIL (CD3+, CD4+, and CD8+ T cells)." (PMID 36010256, 2022). "After recognition of tumor antigens presented by antigen-presenting cells through their MHC class II, activated CD4+ helper T cells (Th cells) release cytokines which are essential for antigen-presenting cells and CD8+ T-cell activation." (PMID 35885563, 2022). "Previous studies have demonstrated high levels of tumor-infiltrating lymphocytes (TIL) with promising prognosis in NSCLC, which infiltrated more CD8 positive, CD3 positive, and CD4 positive TIL." (PMID 35280857, 2022). "CST showed a near-complete tumor response, with a marked improvement in her functional status and simultaneous increases in tumor-specific CD8+ and CD4+ T cells." (PMID 35628206, 2022). "This significant immune response was, in turn, correlated to a) a relatively low expression of PD-L1 on the surface of tumor-infiltrating CD11b+ myeloid cells and b) low expression of PD-1 in the surface of both T CD8+ and CD4+ splenic lymphocytes." (PMID 35922755, 2022). "In contrast to the CD4 and CD8 T cells, F4/80+ macrophages and CD11c+ DCs were more abundant in the WT tissue and increased in the A10E2 and G9 tumor tissues." (PMID 35150340, 2022). "They develop tumors with heterogeneous phenotypes, regarding the expression of CD4 and CD8 markers, including some in which peripheral tumor T cells display a prevalent CD4−CD8− or CD4+CD8− or CD4−CD8+ phenotype." (PMID 35444651, 2022). "AC-Bacteria can significantly increase the proportion of CD4+ T cells and CD8+ T cells in the tumor." (PMID 36120661, 2022). "The use of this iPSC vaccination decreased CD4 + CD25 + FOXP3 + regulatory T cells in the murine model, thus reversing the immunosuppression of the TME while preventing the development of tumours in 75% of mice." (PMID 35626020, 2022). "Using flow cytometry, vaccinated mice, both naïve and tumor-bearing, displayed significant increases in the proportion and number of peritoneal effector memory (CD44+CD62L(low)) CD4+ and CD8+ T cells compared to unvaccinated mice (Day 25)." (PMID 36142437, 2022). "The analysis revealed a negative correlation of galanin expression with the number of several tumor-infiltrating immune cells, including CD8+ and CD4+ T-cells, neutrophils, and natural killer cells in the TME." (PMID 35707368, 2022). "In brief, after systemic administration in xenografted mice, AAV-Her2 detected 75.7% of tumor foci and AAV-CD4 targeted 4.4% of all human CD4+ lymphocytes." (PMID 35890005, 2022). "In human CD4+ T cells, miR-138 represses PD-1, CTLA-4, and FoxP3 expression, and in vivo administration of miR-138 mimics to tumor-bearing mice led to enhanced T-cell–mediated tumor immunity and survival." (PMID 36248881, 2022). "Our findings showed a recruitment of CD4+, CD8+, and CD20+ cells to the tumor microenvironment in rapidly progressing VS." (PMID 36195959, 2022). "These STAT1-positive tumors also exhibited a high degree of immune cell infiltration, especially CD4-, CD8, and FOXP3-positive T cells, suggesting that an active engagement of the immune system with the tumor takes place and that these tumors are immune “hot”." (PMID 35267462, 2022).